IGF2R (insulin like growth factor 2 receptor)
Diseases named in the same sentence as IGF2R in open-access papers (continued):
Sharing a sentence is not in itself a finding about the gene and the disease.
Insulin resistance (15 papers, 2015 to 2025). Increased resistance towards insulin, that is, diminished effectiveness of insulin in reducing blood glucose levels. "IGF2R is located on chromosome 6q26, a region that contains a genetic marker associated with insulin resistance traits in Mexican—Americans." (PMID 38701040, 2024). "Circulating IGF2R is associated with insulin resistance and the rs416572 C allele has been previously shown to be associated with T2D diagnosis." (PMID 38909264, 2024). "MiR-143-3p silencing participates in the development of obesity-mediated insulin resistance, glucose tolerance and lipid accumulation and characterizes the miR-143-3p-IGF2R cascade as a possible target of treating obesity-linked metabolic diseases." (PMID 34485272, 2021). "Additional demonstrations of the association of IGF2R with insulin resistance and glucose homeostasis are based on the discovery of IGF2R genetic variants and soluble circulating IGF2R in both type 1 (T1DM) and type 2 (T2DM) diabetes mellitus." (PMID 32075092, 2020). "Only circulating IGF2R, age, and BMI were independently associated with the degree of insulin resistance, as assessed by the HOMA model." (PMID 25922844, 2015). "As shown in a linear regression model with age, sex, BMI, IGF2R gene polymorphism, and circulating IGF2R as independent variables, only circulating IGF2R, age, and BMI were independently associated with the degree of insulin resistance." (PMID 25922844, 2015). "We further explored the influence of both IGF2R gene polymorphism and IGF2R levels on insulin resistance as assessed by the homeostatic model assessment (HOMA) model." (PMID 25922844, 2015). "Inhibition of miR-143-3p protected against the development of insulin resistance by targeting insulin-like growth factor 2 receptor (IGF2R)." (PMID 38931457, 2024). "Here, we have identified and replenished the circRNF111-miR-143-3p-IGF2R axis as a promising therapeutic target in the alleviation of insulin resistance and lipid deposition of MetS." (PMID 34485272, 2021). "We subsequently validated its biological regulatory function in obesity-induced insulin resistance and lipidosis through sponging of miR-143-3p, which downregulated IGF2R expression." (PMID 34485272, 2021). "A recent study showed significantly elevated levels of circulating miR-143-3p in patients with metabolic syndrome, which, when inhibited in a mouse model, inhibited insulin resistance (IR), and its key target was insulin-like growth factor 2 receptor." (PMID 32962255, 2020). "A further role has been identified in insulin resistance through targeting of the insulin-like growth factor 2 receptor and subsequent activation of the insulin signaling pathway." (PMID 31979312, 2020). "Furthermore, reducing levels of miR-143-3p in mice through anti-miR-143-3p injection into the tail vein was found to mitigate obesity-induced insulin resistance by modulating the expression of the insulin-like growth factor-2 receptor (Igf2r)." (PMID 40941416, 2025). "Since there is increasing evidence of the association between insulin resistance and neurodegenerative disease, the role of IGF-II, which has a higher affinity than IGF-I for IRA/IGF1R hybrids and interacts with IGF2R, including its soluble form, is recommended as a research focus." (PMID 38674097, 2024). "By targeting insulin-like growth factor 2 receptor (IGF2R), miR-143 impairs insulin signaling in 3T3-L1 preadipocytes, while its inhibition protects mice on an HFD against the development of obesity-associated insulin resistance." (PMID 34943849, 2021). "Furthermore, miR-143-3p has been established to target IGF2R along with IGFBP5 thus possibly participates in insulin resistance reported in MetS." (PMID 34485272, 2021). "Therefore, altered Igf2r expression in duodenum might reflect or be related to insulin resistance in patients with GDM." (PMID 38626157, 2024).
Insulin resistance (continued). "Recently, seven markers based on the BMI-sensitive pathway of insulin resistance, adipoR1, adipoR2, ObR, IRβ, IRS-1, IGF-1R, and IGF-2R, have been proposed to develop a new molecular typing system for endometrial cancer." (PMID 31440472, 2019). "However, to the best of our knowledge, there is no study examining its association with insulin resistance and tissue levels of insulin-like growth factor 1 receptor (IGF-1R) and insulin-like growth factor 2 receptor (IGF-2R)." (PMID 33143702, 2020).
Obesity (10 papers, 2014 to 2025). Accumulation of substantial excess body fat. "We report, for the first time, that DHA supplementation during pregnancy in women with obesity normalizes the increased IGF2R levels in male placentas, reducing the risk of adverse outcomes related to the IGF2/IGF2R system in male newborns." (PMID 37408866, 2023). "Insulin-like growth factor receptor 2 (IGF2R) regulates placental nutrient transport, and its soluble form is related to obesity in adults." (PMID 37408866, 2023). "They concluded that prenatal exposure to BPA could influence the differential methylation of IGF2R (cg19196862) at 2 years of age, leading to obesity in the future." (PMID 39519574, 2024). "We first evaluated whether the obesity condition affects the placental IGF2R expression (mRNA and protein)." (PMID 37408866, 2023). "In addition, we observed that the maternal DHA supplementation prevented the increase of the levels of IGF2R induced by maternal obesity in male placentas." (PMID 37408866, 2023). "This opposite effect between the gene expression and the protein levels may suggest the downregulation of the gene expression induced by the increased levels of IGF2R affected by obesity." (PMID 37408866, 2023). "Therefore, the placental expression of its receptor, IGF2R, should be relevant to the biological function of IGF2 and its involvement in the risk of developing obesity in the offspring of women with obesity." (PMID 37408866, 2023). "Therefore, the down-regulation of Peg3 and Igf2 and up-regulation of Igf2r in adipocytes from HFD-induced obesity mice is specific to B6 mice." (PMID 24416415, 2014). "If the placental expression of IGF2R is altered in women with obesity is unknown." (PMID 37408866, 2023). "For example, bioinformatic comparison of transcriptomes in polycystic ovary syndrome (PCOS), obesity, and T2DM identified jointly dysregulated genes (including IGF2R, the insulin-like growth factor 2 receptor) and network “hub” proteins such as STAT3, IL1B, and PF4." (PMID 41303351, 2025).
diabetes (8 papers, 2011 to 2022). "IGF2/IGF2R signaling has been implicated in metabolic regulation and diabetes risk with circulating IGF2R associated with type two diabetes mellitus (T2DM)." (PMID 33704916, 2021). "The evaluation of the IGF2R genotypes distributions in diabetes patients revealed that the CC allele had a higher frequency among these patients than the others investigated alleles (CT or TT), thus affecting the circulating IGF2R levels distribution and T2D development." (PMID 30445764, 2018). "However, the role of genetic variants of the IGF2R system in type 2 diabetes mellitus is still unclear." (PMID 30445764, 2018). "Indeed, the association between IGF2R genotype and diabetes-related phenotypes including age, gender, and BMI became less apparent or disappeared after controlling for circulatory IGF2R." (PMID 25922844, 2015). "Taken together with the association of IGF2R gene polymorphism and soluble IGF2R to diabetes in the present study, further investigation to elucidate how soluble IGF2R fits in the complex system of IGF and how IGF2 together with IGF2R influence the susceptibility to type 2 DM is warranted." (PMID 25922844, 2015). "In the present study we demonstrated that soluble IGF2R levels were associated with IGF2R genotype, and it is likely that IGF2R gene polymorphism may influence diabetes-related phenotypes partly through its association with the availability of soluble IGF2R." (PMID 25922844, 2015). "The free energy of the interaction of miR-466 and ID00436.3p-miR with mRNA of the BACH2, FASLG, HEMGN and IGF2R genes, which are involved in diabetes diseases, is −105 ± 1 kJ/mole with GU repeats in the 3′UTR." (PMID 35627185, 2022). "In order to exclude the potential confounding effect of longstanding diabetes and diabetes treatments on circulating IGF2R, only subjects with newly diagnosed diabetes (n = 97) were studied together with subjects having normal glucose tolerance and IFG/IGT." (PMID 25922844, 2015). "Given diabetes is one of the strongest risk factors for the development of AD and a common comorbidity, dysregulation of IGF2 signaling through IGF2R may contribute to the neuropathology of AD." (PMID 33704916, 2021). "Coding polymorphisms in the consensus Chr 17 area included those linked to cancer (Fndc1, Tiam2, Zdhhc14 Has1), growth and development (Igf2r, Afdn, Tiam2, T2), immunology or diabetes itself via the energetic electron transfer chain (Tiam2, Pde10A) or basal thermal metabolism." (PMID 31661517, 2019). "However, whether circulating IGF2R is determined by IGF2R gene variants and how soluble IGR2R is related to diabetes in adults are currently unknown." (PMID 25922844, 2015).
osteosarcoma (8 papers, 2011 to 2023). A usually aggressive malignant bone-forming mesenchymal neoplasm, predominantly affecting adolescents and young adults. "The insulin-like growth factor 2 receptor (IGF2R) has been identified as an overexpressed target in all types of osteosarcoma (OS) cells, making it a suitable target for RIT." (PMID 37570809, 2023). "IGF-R expression at the mRNA level has been detected in osteosarcoma cell lines: in particular, IGF-2R was overexpressed in all tested osteosarcoma cell lines." (PMID 24216993, 2013). "Followup of these findings in osteosarcoma is needed to better understand how genetic variation in IGF2R contributes to its etiology." (PMID 21437228, 2011). "Additionally, these studies showed that targeting IGF2R on canine-patient-derived osteosarcoma tumors in mice with radioimmunotherapy resulted in effective tumor regression." (PMID 37570809, 2023).
colorectal cancer (7 papers, 2010 to 2025). A primary or metastatic malignant neoplasm that affects the colon or rectum. "Similarly, the Igf2r D1310 frameshift deletion mutation identified in our murine models is shared by 3.8% of MSI-H colorectal cancer patients, 3% of MSI-H endometrial cancer patients and 1.4% of MSI-H stomach cancer patients." (PMID 41256707, 2025). "In colorectal cancer, mutations have been found in a number of genes with key cellular roles, such as growth factor receptors (TGFBR2 and IGF2R), genes involved in apoptosis (BAX), as well as genes relevant for DNA repair (MSH3, MSH6)." (PMID 20979647, 2010). "But the expression of IGF1R, IGF2R, and PPARG was negatively correlated with the number of infiltrated CD8+ T cells in colorectal cancer; the related antidiabetic drugs may produce negative effect on anti-PD1 tumor inhibition." (PMID 36033393, 2022).
hepatocellular carcinoma (7 papers, 2011 to 2025). A malignant tumor that arises from hepatocytes. "It was previously shown that IGF-2R gene was significantly associated with human hepatic carcinoma." (PMID 26683100, 2016). "With these IGF antibody arrays, we measured the expression levels of 10 members of IGF signal family and found that IGF-2R and IGFBP-2 were increased in hepatocellular carcinoma (HCC) tissues compared with adjacent tissues." (PMID 23071652, 2012).
liver cancer (7 papers, 1997 to 2025). An epithelial or non-epithelial malignant neoplasm that arises from the liver. "Kaplan–Meier analysis subsequently showed that C2orf27A and IGF2R were negatively correlated with the survival time of liver cancer patients, whereas CFB and PON1 were associated with favorable survival times." (PMID 33495404, 2021). "Loss of heterozygosity (LOH) at the IGF2R locus with mutations in the remaining allele have been reported in liver cancers and recently in two high-grade cases of ductal carcinoma in situ of the breast." (PMID 9413941, 1997). "However, IGF2R – a tumor suppressor in liver cancer – is mutated in HCC with loss of heterozygosity." (PMID 23724146, 2013). "Our research described the regulatory role of IGF2 in the TME from a new perspective, targeting the IGF2/IGF2R/MAPK axis to potentially suppress the CCA in primary liver cancer." (PMID 39674501, 2025). "The loss of heterozygosity of IGF2R can lead to development of certain types of tumors (e.g. lung, breast, or liver cancer), and in addition, knockdown of IGF2R induces apoptosis in hemangioma cells." (PMID 32877466, 2020). "Among the four genes, C2orf27A and IGF2R were found to be positively correlated and CFB and PON1 were negatively correlated with the stage and tumor grade of liver cancer." (PMID 33495404, 2021).
cervical carcinoma (6 papers, 2012 to 2023). A carcinoma arising from either the exocervical squamous epithelium or the endocervical glandular epithelium. "Thus, the loss of IGF2R induces caspase-dependent apoptosis and drug sensitivity in cervical cancer cells." (PMID 31748500, 2019). "Moreover, loss of IGF2R induced caspase-mediated apoptosis in cervical cancer cells." (PMID 31748500, 2019). "In cervical cancer, it was shown that upregulation of IGF-2R helped cells escape lysosomal-dysfunction-induced apoptosis via the transport of M6P-tagged cathepsins." (PMID 37834454, 2023). "IGF2R, insulin-like growth factor 2 receptor, is currently considered a tumor suppressor gene, but it is upregulated and correlated with poor prognosis in cervical cancer and glioblastomas." (PMID 35186733, 2022). "Taken together, IGF2R has an oncogenic role through transportation of M6P-tagged cargo in cervical cancer and can be used as a predictive biomarker for prognostic classification." (PMID 31748500, 2019). "A publicly available DNA microarray dataset revealed that three of the candidates (PGM1, FNDC3B, and IGF2R) were aberrantly expressed in cervical cancer tissues relative to normal cervix tissues." (PMID 31748500, 2019). "Transcriptome analyses in IGF2R-knockdown cervical cancer cells identified 317 and 287 genes to be commonly upregulated or downregulated, respectively, by IGF2R knockdown (and GEO accession number: GSE137998)." (PMID 31748500, 2019). "Consistent with the DNA microarray analysis results, immunohistochemical staining showed higher IGF2R expression in cervical cancer tissues (four cases out of six), whereas only weak staining was observed in their corresponding normal cervical tissues." (PMID 31748500, 2019). "Immunocytochemical analyses showed that IGF-2 bound to IGF2R on cervical cancer cells and other cancer cells, as previously reported." (PMID 31748500, 2019). "Under normal conditions, both cathepsin B and L are partly co-localized with IGF2R in cervical cancer cells." (PMID 31748500, 2019). "It is noteworthy that high IGF2R expression was also unfavorable for patients with stage I cervical cancer, indicating its clinical utility as a prognostic marker during early diagnosis." (PMID 31748500, 2019). "In conclusion, we have shown that high IGF2R expression is correlated with poor prognosis in cervical cancer." (PMID 31748500, 2019). "Here, on the basis of transcriptome analysis of TCGA and GEO open datasets, we show that IGF2R is upregulated and correlated with poor prognosis in cervical cancer." (PMID 31748500, 2019). "Several experiments using cervical cancer cell lines revealed that IGF2R depletion induced apoptosis, decreased cell viability, and increased vulnerability to certain anticancer drug cisplatin." (PMID 31748500, 2019). "Overall survival analyses also revealed that high IGF2R expression is a poor prognostic factor not only for cervical cancer but also for breast and ovarian cancers." (PMID 31748500, 2019). "Surprisingly, our RNAseq data analysis showed that IGF2R is also a poor prognostic factor for early-stage cervical cancer, suggesting its role in tumor recurrence." (PMID 31748500, 2019). "Here, we identified IGF2R as a poor prognostic biomarker for cervical cancer patients and showed that it has oncogenic functions, contrary to previous reports about other cancers." (PMID 31748500, 2019). "With regard to cervical cancer, however, IGF2R expression was increased in cancer tissues, and patients with high IGF2R expression had worse prognoses." (PMID 31748500, 2019). "By comparison with receptor-positive HeLa human cervical carcinoma cells, the M6P/IGF2R content of FRL14/IGF2R wt-1 and FRL14/IGF2R wt-2 cells was estimated to be 2.5 and 2.1 pmol/mg total cell protein, respectively." (PMID 22521359, 2012). "Recent work in cervical cancer suggested that IGF2R knockdown had an autophagic inhibitory effect." (PMID 34365465, 2021).
cervical carcinoma (continued). "Here, we identified IGF2R as a novel biomarker for poor prognosis in patients with cervical cancer." (PMID 31748500, 2019). "Finally, we focused on the gene IGF2R because its mRNA expression is higher than that of other oncogenic receptors in cervical cancer tissues." (PMID 31748500, 2019). "Patients with high IGF2R expression showed significantly worse cervical cancer prognosis." (PMID 31748500, 2019). "Furthermore, the expression of IGF2R can be used as a prognostic biomarker for cervical cancer patients." (PMID 31748500, 2019). "IGF2R has a role opposite to its currently recognized tumor suppressive role, and its function as a transporter of M6P cargo to maintain lysosome homeostasis is important in cervical cancer cells." (PMID 31748500, 2019). "Therefore, IGF2R blockade could be critical to cervical cancer cells, and the blockade of this Golgi-to-lysosome transport system could be a potential therapeutic target." (PMID 31748500, 2019). "Therefore, pre-emptive medical care may yield clinical benefits for early-stage cervical cancer patients with high IGF2R expression." (PMID 31748500, 2019). "However, our study shows that, in cervical cancer cells, loss of IGF2R did not alter the major receptor tyrosine kinase pathways." (PMID 31748500, 2019). "Therefore, we considered that novel mechanisms of oncogenic IGF2R may exist in cervical cancer." (PMID 31748500, 2019). "To investigate the biological significance of IGF2R and IGF1R in cervical cancer cells, we analyzed six cervical cancer cell lines using gene knockdown." (PMID 31748500, 2019). "We further investigated the relationship between IGF2R and M6PR in cervical cancer cells." (PMID 31748500, 2019). "In cervical cancer, IGF2R expression was correlated with clinical staging but not with distal metastasis or primary therapy outcomes." (PMID 31748500, 2019). "Although neither IGF2R nor IGF1R knockdown altered cell cycle status in cervical cancer cells, only apoptotic cells and caspase activities were significantly increased by IGF2R knockdown." (PMID 31748500, 2019). "Considering that progression-free survival was shorter in patients with high IGF2R expression (not shown), the receptor may play a role in recurrence in cervical cancer patients." (PMID 31748500, 2019). "In contrast to IGF2R, M6PR knockdown did not influence intracellular cathepsins, protein ubiquitinylation, or cervical cancer cell survival." (PMID 31748500, 2019).